CD4 (CD4 molecule)
Diseases named in the same sentence as CD4 in open-access papers (continued):
Sharing a sentence is not in itself a finding about the gene and the disease.
tumor (continued). "To investigate the role of other tumor fighting immune cells besides CD8+ and CD4+ T cells, we had a look at the NK cells from the patient’s blood, gated as CD3- CD56+ cells." (PMID 38650948, 2024). "Moreover, the release of tumor-associated antigens (TAAs) or tumor-specific antigens (TSAs) from damaged tumor cells and their subsequent presentation by antigen-presenting cells (APCs) stimulate adaptive immune responses, which involve the activation of antigen-specific CD4+ and CD8+ T cells." (PMID 38464532, 2024). "CXCL8 modulates the TNBC immune microenvironment by controlling the infiltration of CD4+ and CD8+ T cells and increasing CD274 (PD-L1) expression, unveiling potential therapeutic targets for anti-tumor immunotherapy." (PMID 38791448, 2024). "Meanwhile, studies have found that LAG-3 and PD-1 were widely co-expressed on CD4+ and CD8 + T cells, especially on tumor-infiltrating T cells." (PMID 38177102, 2024). "The higher the risk index, the lower was the abundance of cytotoxic immune cells such as CD4+ T and CD8+ T cells as well as the immune score and tumor purity." (PMID 38713284, 2024). "MDM2 peptides activate CD4+ helper T lymphocytes, and activated helper T lymphocytes secrete cytokines such as IFN-γ, activate CTLs, and directly kill tumor cells via granzyme B92." (PMID 39263534, 2024). "To investigate this, we compared glycolytic parameters among tumor cells and CD8+ T cells, CD4+Foxp3– cells (effector T cells [Teffs]), and CD4+Foxp3+ cells (Tregs) within the TME from established B16-YFP tumors excised from mice treated with LDHi for 10 days." (PMID 39225102, 2024). "Tregs and CD163+macrophages had a higher tendency to infiltrate into the tumor center compared with B cells, CD8+T cells and CD4+T helper cells." (PMID 39053947, 2024). "Sarcomatoid tumors have lower levels of CD4+ and CD8+ T cells in the tumor tissue, which are required for an effective anti-tumor response." (PMID 39410037, 2024). "CD4+ Tex and CD8+ Tex cells were exclusive to four tumor groups, with CD8+ Tcyto cells being most prevalent in the normal sample." (PMID 39112478, 2024). "The CD4/CD8 ratio, which was ~1.1 in the spleen, increased towards a ratio of about 4.0 in the tumor." (PMID 39000582, 2024). "Altogether, these findings indicate that while mice treated with anti-CTLA-4, alone or in combination with anti-PD-1, display the most dramatic increase in IFN-γ-producing Th1-like CD4 T cells within the tumor, anti-PD-1 also incites IFN-γ+ CD4 T cells." (PMID 38187708, 2024). "And the activation of Wnt-β-catenin signaling pathway displayed an insufficient T cell infiltration in the tumor microenvironment, consistent with the results that TFP tumors presented reduced immune infiltration of activated CD4 T cell and CD8 T cell." (PMID 38331878, 2024). "Overall, these findings show that CR705Parp7KO tumours had a higher proportion of cytotoxic CD8+ T cell infiltration, as well as a lower relative amount of PD-1High CD4+ Tregs vs. effector memory CD4+ T cells." (PMID 39867896, 2024). "CD4 and ALOX5 gene expression level significantly differed between tumour samples when compared to normal brain tissue in both GBM and LGG." (PMID 38816839, 2024). "Immunofluorescence analysis demonstrated a significantly elevated presence of CD4+ and CD8+ T cells in the tumor tissues of mice treated with rPRV-iPD-L1 and rPRV-RFP." (PMID 39205202, 2024). "Regarding the tumor infiltrating lymphocytes (TILs) compartment, PeptiCRAd and PeptiCRAd+ DAC, despite a lower CD4+ T cell infiltration, showed a reduced percentage of intratumoral Tregs (CD25+, FOXP3+)." (PMID 38596301, 2024). "Our findings demonstrated a significant reduction in the expression of CD4, CD8, and granzyme B (GZMB) in Nfkb2‐overexpressing MC38 tumor tissues and CRC tumor samples with high NFKB2 expression." (PMID 38660687, 2024).
tumor (continued). "The inulin-presented groups (inulin gel and Oxa@HMI hydrogel groups) exhibited significantly higher levels of tumor-infiltrating CD8+ T and CD4+ T cells compared to the PBS group detected by flow cytometry and immunofluorescence staining assays." (PMID 38721274, 2024). "With increasing pore size (7.8 nm, 10.3 nm, and 12.9 nm), MSN induced CD4+ T cells to secrete high levels of IFN-γ and IL-4, and CD8+ T cells to secrete IFN-α, which induced a stronger immune response and tumor suppression effect." (PMID 39334825, 2024). "Specifically, the majority of CD8+T cell clusters were significantly enriched in adjacent normal tissue samples, whereas CD4+T cell clusters including CXCL13+T cells and Treg cells showed higher enrichment in tumor samples." (PMID 38311726, 2024). "The shift in macrophage polarization in Rgs5KO B16-OVA tumors also correlated with increased numbers of endogenous CD4+ and CD8+ T cells in the tumor environment." (PMID 39286984, 2024). "Tumours enriched with inflammatory genes, particularly in IFN- and TNF-α-related pathways and CD4+ T cells in an inflamed tumour microenvironment, were associated with better response to chemotherapy." (PMID 39409156, 2024). "We here showed that the effective T cells, including CD4+T, CD8+T and Tprolif in tumor tissues have higher levels of cuproptosis than T cells from PBMCs of tumor patients, illustrating that the reduction of effective T cells within tumor tissues might be caused by cuproptosis." (PMID 39575251, 2024). "This dual modality not only targets the tumor cells more effectively but also stimulates the immune system, as evidenced by the significant increase in CD3+CD4+ and CD3+CD8+ T cell populations within the tumor microenvironment." (PMID 39045563, 2024). "The therapy also enhanced anti-tumor immunity, as evidenced by an increased frequency of CD8+ effector memory T cells and CD8+/CD4+ central memory T cells." (PMID 39861805, 2024). "CD4+ and CD8+ T lymphocytes as well as NK cells were found infiltrating all these tumor types, albeit in different proportions." (PMID 38790160, 2024). "It is possible to more correctly forecast the trajectory of tumor development and the prognosis of patients by determining the presence of CD3+, CD4+, and CD8+ T cells in the tumor lesion area." (PMID 38549936, 2024). "The ratio of TH/TC (CD4/CD8) was lower in tumor-rich regions, suggesting a higher percentage of TC among tumor-infiltrating T cells in MCL." (PMID 39001353, 2024). "The Response group displayed dense clusters of CD4+ and CD8+ T cells within and surrounding the tumor, indicative of a highly active (“hotter”) immune response." (PMID 38726002, 2024). "Human leukocyte antigen class II (HLA‐II) is vital in presenting tumour antigens to CD8+ and CD4+ T cells, thereby aiding in the successful eradication of cancer cells." (PMID 38451000, 2024). "The markers used to characterize the immune and tumor compartments of the iTME were: CD3, CD4, CD8a, FOXP3, PD-1, PD-L1, CD68, CD33, and pan-keratin (PanCK)." (PMID 38898200, 2024). "Significant tumor microenvironment changes were observed in pCR patients, including reduced VEGF+ cells and CD4+Foxp3+ Treg cells, and increased perivascular CD4+ T cells, CD39+CD8+ T cells, and M1 macrophages." (PMID 39465257, 2024). "Immunophenotyping of residual tumors showed that TKI treatment with either sorafenib or lenvatinib led to reduced tumor-infiltrating CD8+ T cells and increased immunosuppressive CD4+Foxp3+ regulatory T cells (Treg)." (PMID 38310091, 2024). "Robust CD4+ and CD8+ T‐cell depletion in peripheral blood samples of indicated groups was confirmed via flow cytometry staining seven days after initiating tumor vaccine treatment." (PMID 38298111, 2024). "These vaccines also increased T-lymphocytes of the CD4 and CD8 subsets infiltration within tumor fields." (PMID 38289597, 2024).
tumor (continued). "On the other hand, in the tumor compartment, the number ranged from 0 to 8 for FOXP3, from 0 to 12 for CD4, and from 1 to 24 for CD8." (PMID 37567864, 2024). "The CD4-depleted mice treated with DMBA had significantly increased tumor-free survival and overall survival as well as decreased tumor-volume growth over time when treated with SQV." (PMID 39339897, 2024). "The immune response was mediated by CD4+ T cells, CD8+ T cells, and B cells, and the vaccine showed anti-angiogenic effects by reducing tumor vessel density." (PMID 39081320, 2024). "In the splenectomy group, they additionally observed a lower ratio of effector T cells (CD8 + /CD4 +) to immunosuppressive regulatory T cells (FOXP3 +), suggesting an impaired anti-tumor immune response." (PMID 39710775, 2024). "TIM-3 expression was also more pronounced in CD4+ and CD8+ T cells from Patients exhibiting a higher tumor grade (G3)compared to those with a lower tumor grade (p=0.010 and p=0.042)." (PMID 39206199, 2024). "In the tumor microenvironment (TME), the expression levels of CD4+ T cells and CD8+ T cells of different phenotypes were associated with TLSs." (PMID 39009684, 2024). "Hypoxia, which is frequently brought on by disorganized and inadequate tumor microcirculation, impairs the ability of CD8+ and CD4+ T lymphocytes to perform effector tasks and promotes the growth and migration of immune-suppressive cells." (PMID 39712007, 2024). "Several studies evaluating different T cell-redirecting bispecific antibodies reported that they activate both CD4 + and CD8 + T cells, which contribute to target cytotoxicity, and their activity correlates with tumor antigen expression." (PMID 38429446, 2024). "ST and mIHC results proved that CD8+T cells, CD4+T cells, and NK cells are mostly located on the non‐tumor side of the frontier region, while MAIT infiltrates into the tumor side, suggesting the initial anti‐tumor role of MAIT in the leading‐edge area." (PMID 39716897, 2024). "Taken together, these results suggest that the presence of DCC impairs CD4 and CD8 cell activation in response to IAV infection, favoring tumor cells persistence." (PMID 38645169, 2024). "Our study is in line with these results regarding the MHC/co-receptor match, even if the MHC context and the MHC/co-receptor mismatch are different and these features can influence the capacity of CD4+ and CD8+ TCR-T to eradicate tumor cells." (PMID 38545119, 2024). "A distinct overexpression of CD1c, CD2, CD3, CD4, CD11c, CD14, CD20, CD44, CD56, CD105, CD146, and CD209 was identified in LCa patients compared to healthy controls, correlating positively with tumor presence." (PMID 38902710, 2024). "DC subsets (i.e., cDC1 and cDC2) have distinct phenotypes and functions that can differentially affect anti-tumor immune responses (cDC1: CD8+ T cell activation and CD4+ T cell licensing; cDC2: CD4+ T cell priming)." (PMID 38389838, 2024). "Few but detectable TIL are present in the tumor TCR-T-treated mice only (untreated vs total GMTC: p= 0.081; untreated vs CD8+ GMTC: p= 0.078; untreated vs CD4+ GMTC: p< 0.05; total UTC vs total GMTC: p= 0.079 and total UTC vs CD4+ GMTC: p= 0.09)." (PMID 38545119, 2024). "Various chemokines and cytokines drive cDC1s to tumour tissues, where they internalise and process tumour antigens onto HLA‐I and HLA‐II, which are subsequently presented to CD8+ and CD4+ T cells." (PMID 38997802, 2024). "Transgenic mice expressing dominant-negative TβRII in CD4+ and CD8+ T cells exhibit resistance to tumor growth, indicating the necessity of TGF-β in those T cell lineages for tumor growth." (PMID 38675493, 2024). "As the major sub-population of both CD4 and CD8 T-cell populations, the prognostic significance of Tem in tumor has long been controversial." (PMID 39100667, 2024).
tumor (continued). "To investigate the effects of BMI on immune infiltration in OTSCC, we measured the expression of CD4, CD8, CD20, PD1 in tumor immune microenvironments (TIMs) involving a total of 27 patients with available of specimen by IHC." (PMID 38923758, 2024). "In many types of cancers, PD-1 is highly expressed in tumour-infiltrating lymphocytes (TILs), including both CD4+ and CD8+ T cells, and the upregulated protein expression is correlated with tumour size and worse overall survival of cancer patients." (PMID 38359715, 2024). "CD4+ and CD8+ T cells that were 100 μm away from the tumor center were more likely to be activated with better immune response as well as having better correlation." (PMID 39703499, 2024). "Despite the impaired in vitro proliferation, our IL-21R enhanced the persistence of CD4+ TCR-T in vivo, which led to increased tumor-infiltrating cells." (PMID 38643203, 2024). "The expression of IDO2 curtails the proliferation of CD4+ and CD8+T cells, and impedes the infiltration of CD4+ T cells into tumor sites." (PMID 39492834, 2024). "Considering that some tumors of the HM‐NPs group were not completely inhibited, we performed H&E staining and immunohistochemical staining of CD4+ and CD8+ T lymphocytes on these tumor tissues." (PMID 38353384, 2024). "Of these, CD8+ T lymphocytes exhibit cytotoxic activity on tumor cells, and CD4+ and CD8+ lymphocytes suppress tumor recurrence and achieve tumor cell clearance, in the memory phase." (PMID 38715617, 2024). "We found that the proportions of effector memory CD4+ T cells, effector memory CD45RA+ CD4+ T cells, and effector memory CD45RA+ CD8+ T cells were increased in CRC, reflecting active immune responses to tumor signals." (PMID 38735538, 2024). "We further demonstrated that αPD-L1scFv-hFc significantly increased activation marker CD107a in CD4+ T and CD8+ T cells in CT26-derived tumor mice." (PMID 38953994, 2024). "Mice subjected to both treatments showed an increase in numbers relative to IG-IR alone, however infiltration was still limited with an average of only ~1,100 profiled immune cells recovered per tumor, with CD8+ and some CD4+ cells predominating." (PMID 38498459, 2024). "After the euthanasia of murine subjects, an assessment of oncolytic efficacy was performed through flow cytometry analysis of murine blood and tumor tissue, targeting CD83, CD86, CD8, and CD4." (PMID 39062070, 2024). "In ICC, CD4+ tumor-infiltrating lymphocytes (CD4+ TILs) predominantly localize in the peritumoral region, while CD8+ tumor-infiltrating lymphocytes (CD8+ TILs) are primarily found within the intratumoral tissues." (PMID 39452125, 2024). "It has been shown that blocking IL-6 enhances the therapeutic effect of immunotherapy by inducing and recruiting higher levels of CD4 + /CD8 + effector T cell production and recruitment in the tumor microenvironment." (PMID 38717677, 2024). "Activated by MHC molecules, CD4 + helper T cells differentiate into subtypes such as Th1 and Th2, assisting CD8 + T cell-mediated cytotoxicity and playing an active role in tumor immunity." (PMID 39741315, 2024). "αβ T cells are further divided into CD4+ T cells (helper T cells) and CD8+ T cells (cytotoxic T cells (CTLs)), both of which play crucial roles in anti-tumor immunity." (PMID 38792234, 2024). "The percentages of different immune cell subtypes, including CD3+ T cells, CD4+ T cells, CD8+ T cells, regulatory T cells, macrophages, NK cells, and B cells, in the tumor and stromal regions were quantified." (PMID 38888366, 2024). "Strikingly, the Western blot expression intensity of tumor exosomal ENPP1 also shown an inverse correlation with CD8+ T cells and CD4+ T cells infiltration, respectively." (PMID 38498770, 2024). "This process aims to stimulate the generation of CD4+ and CD8+ T cells, thereby eliciting an immune response that contributes to anti-tumor effects." (PMID 39772046, 2024).
tumor (continued). "Treatment of mammary tumor-bearing mice with PLX3397 (Pexidartinib), a CSF-1R tyrosine kinase inhibitor, significantly reduced the number of TAMs and resulted in delayed tumor growth stimulated by an increase in CD8 + T cells and a decrease in CD4 + T cells." (PMID 39003350, 2024). "Particularly, combination treatment of DXR and anti-PD-1 treatment significantly increased CD4+ IFN-γ+ and significantly decreased M2 macrophage populations in the tumor microenvironment." (PMID 38609378, 2024). "The inflammation induced by BRAFi recruits cytotoxic GrzB+ CD4+ and CD8+ T cells right into the tumor center away from the tumor margin where T cells are localized in untreated tumors." (PMID 38631706, 2024). "While CD8+T cells are typically favored for targeting tumors, evidence suggests that after DCs phagocytose apoptotic tumor cells, the antigens can still be presented on MHC class II molecules, thereby activating tumor-specific CD4+ T cell responses." (PMID 38835772, 2024). "To further investigate the effect of NACT ± P on T cells, we stained paired tumor samples from the 64 patients with a 7-color immunofluorescence panel (CD4, CD8, PD-1, Ki67, ActCasp3, panCK) to analyze changes in tumor cells and T cell subsets upon treatment." (PMID 39013886, 2024). "Note that with local thresholding, the MLE for CD3ε and CD4 are relatively consistent at ~ 75% in both CT26 and 4T1 tumor models." (PMID 38605049, 2024). "Tumor antigens released by cancer cells are processed by antigen-presenting cells (APC) and presented to the CD4+ and CD8+ lymphocytes, triggering the immune response that enhances tumor destruction." (PMID 38279265, 2024). "Within the tumor microenvironment (TME), regulatory T cells (Tregs) are a subset of CD4+ T cells that mediate immune tolerance." (PMID 38725845, 2024). "After in vivo injection, SLPs are engulfed and presented by APCs to autologous CD4+ and CD8+ T cells, and then these primed T cells circulate to the tumour and perform cytotoxicity." (PMID 38183840, 2024). "Consistent with previous observations, we found that CD8 + T cells were the predominant subtype of T cells in penile tumor samples (p = 0.0001), with an average CD8:CD4 ratio of 3.11 (ranging from 0.43 to 9.20)." (PMID 38280010, 2024). "Due to the ability of DCs to cross-present in both CD4+ and CD8+ T cells, their potential in priming antigen-specific T cells to enhance anti-tumor and anti-viral immunity are highly investigated." (PMID 39339919, 2024). "More specifically, matched resection tissue from pre-treatment and 2–9 months post-treatment showed a significant increase in CD4+ and CD8+ T cells within the tumour as well as areas adjacent and distant from where G207 was inoculated." (PMID 38732225, 2024). "To analyze the characteristics of the TIME in different tumor regions, we first detected the expression of immune markers including CD4+, CD8+, Foxp3+, CD20+, CD68+, LAMP3+, PD-1+ TILs, and PD-L1 in different tumor regions using IHC." (PMID 38254190, 2024). "In the presence of Th1 cytokines during the infection, these tumor-specific antigens activate CD4+ and CD8+ T cells, which infiltrate the tumor and kill cancer cells more effectively." (PMID 38807760, 2024). "Our data highlight the exercise-induced remodelling of peripheral lymphocyte subpopulations and lymphocyte infiltration in prostate tissue, characterized by CD4+, CD8+ and CD68+ cells, which reinforce the anti-tumour role of exercise." (PMID 37171559, 2024). "Compared to the control groups, tumor samples exhibited significantly higher proportions of both CD8+ (67.4%) and CD4+ (44.9%) T lymphocytes (p < 0.05)." (PMID 38792013, 2024). "Specifically, anti‐tumor immune cells, such as cytotoxic CD8+ T cells, T‐helper CD4+ cells, NK cells, and M1 TAMs increased, whereas immunosuppressive cells, such as MDSCs decreased." (PMID 39297408, 2024).